ESRP1 (epithelial splicing regulatory protein 1)
Diseases named in the same sentence as ESRP1 in open-access papers (continued):
Sharing a sentence is not in itself a finding about the gene and the disease.
ovarian carcinoma (continued). "An enforced ESRP1 expression in the ovarian cancer cell line SKOV3, significantly reduced the level of the mesenchymal cell-specific CD44 isoform 4 and increased levels of CD44 variant isoforms as well as caused overall switching from mesenchymal to epithelial phenotype of cells." (PMID 38106992, 2023). "While ESRP1 has been frequently reported as a tumor suppressor in various cancers, its pro-tumorigenic role has also been shown in some cancers, such as breast and ovarian cancers, indicating that ESRP1 plays a dual role in cancer progression depending on the cancer type." (PMID 38110955, 2023). "Contrarily, the negative association between ESRP1 expression and patient survival as well as the pro-tumorigenic role of ESRP1 have been reported in some cancers, such as breast and ovarian cancers." (PMID 38110955, 2023). "However, the pro-tumorigenic roles of ESRP1 have been revealed in some cancers, such as breast and ovarian cancers." (PMID 38110955, 2023). "A 2020 study identified that pervasive overexpression of ESRP1 in ovarian cancer is dependent on the expression of circ-0005585, which acts as an miRNA sponge for the ESRP1-specific miRNAs miR-15a/15b/16 and miR-23a/b, by expressing mutual miRNA targets as the 3′UTR of ESRP1." (PMID 34769047, 2021). "An extensive literature search revealed that ESRP1 was also overexpressed in ovarian cancer tissues; therefore, we suggested that circ-NOLC1 could bind with ESRP1 and modulating CDK1 and RhoA expression." (PMID 33483472, 2021). "Why ESRP1 was highly expressed in ovarian cancer remained unclear." (PMID 32467669, 2020). "For example, SOX9, MYB, and ESRP1 promote ovarian cancer cell proliferation." (PMID 32076467, 2020). "We found that Rac1b was significantly down-regulated in ovarian cancer cells overexpressing ESRP1." (PMID 32467669, 2020). "In summary, ESRP1 plays a comprehensive role in progression of ovarian cancer." (PMID 32467669, 2020). "ESRP1 could suppress tumorigenic potential in various cancers including colorectal cancer, pancreatic cancer and ovarian cancer." (PMID 30640723, 2019). "The role of B7-H4 may be similar to that of ESRP1 in epithelial ovarian cancer." (PMID 36609273, 2023). "However, the oncogenic role of ESRP1 in cancer remains unclear, whereas some studies have reported its pro-tumorigenic roles in some cancers, including breast and ovarian cancers." (PMID 38110955, 2023). "Thus, we hypothesized that circ-NOLC1 might participate in ovarian cancer tumorigenesis and progression by binding the ESRP1, thus modulating RhoA and CDK1 expression." (PMID 33483472, 2021). "The fact that nuclear ESRP1 and ESRP2 overexpression were strongly associated with unfavorable prostate cancer phenotype and poor patient outcome is in line with previous studies describing a link of high ESRPs expression and an unfavorable phenotype in breast and ovarian cancer." (PMID 33339518, 2020). "Furthermore, we shed light on the mechanism leading to high expression of ESRP1 in ovarian cancer." (PMID 32467669, 2020). "However, it remains unclear whether high expression of ESRP1 based post-transcriptional alternative splicing regulation of mRNAs could link ovarian cancer progression." (PMID 32467669, 2020). "However, the factors leading to the high expression of ESRP1 in ovarian cancer are still unclear." (PMID 32467669, 2020). "In ovarian cancer (OC), circ-NOLC1 binds to ESRP1 and upregulates CDK1 and RhoA expression to promote OC progression." (PMID 40864495, 2025). "In particular, the up- and down-regulation of RBM24 and ESRP1, respectively, represent a main regulator of EMT in ovarian cancer cells." (PMID 38365970, 2024). "They showed that ESRP1 inhibited cell migration by inducing MET and stimulated cell proliferation in ovarian cancer cells." (PMID 36609273, 2023).
ovarian carcinoma (continued). "ESRP1 is a RBPMS2-binding partner, Its expression is correlated with DNA methylation in ovarian cancer cells and can regulate methylation in non-small cell lung cancer cells." (PMID 35137653, 2022). "Overexpression of ESRP1 and/or ESRP2 has been described in various malignant tumors, such as pancreatic ductal adenocarcinoma, oral squamous carcinoma, ovarian cancer, and luminal-type breast cancer." (PMID 33339518, 2020). "In order to clarify the effect of ESRP1 on prognosis of ovarian cancer patients, we screened TCGA ovarian cancer samples, stage III and IV, absence of macroscopic disease after tumor cytoreductive surgery." (PMID 32467669, 2020). "Increased nuclear ESRP1 and ESRP2 staining in comparison to normal tissues was also found in several other tumor entities, including pancreatic ductal adenocarcinomas, oral squamous cell carcinomas, ovarian carcinomas, and colorectal carcinomas." (PMID 33339518, 2020). "However, the cancer-promoting effect of ESRP1 has not been conclusive, especially in ovarian cancer." (PMID 32467669, 2020). "Epithelial splicing regulatory protein-1 (ESRP1), a key negative splicing regulator in epithelial-mesenchymal transition (EMT), has been proven to be overexpressed and may plays a role in epithelial ovarian cancer (EOC) progression." (PMID 32467669, 2020).
pancreatic cancer (20 papers, 2016 to 2025). "ESRP1 and 2 expression are linked to low cell motility, and high level of ESRP1 in pancreatic cancer patients, correlating with a favourable prognosis." (PMID 27911856, 2017). "Another study suggested that the role of the miR-23a in the TGF-β1-induced EMT might also be associated with Epithelial Splicing Regulatory Protein 1 (ESRP1) expression in pancreatic cancer cells." (PMID 30577536, 2018). "For instance, relevant studies have shown that ESRP1 overexpression reduces the migration and proliferation of pancreatic cancer cells in vitro, and rarely produces liver metastases in vivo." (PMID 40528239, 2025). "Patients with high ESRP1 protein expression exhibited a significantly longer overall survival, and ESRP1 attenuated liver metastases in pancreatic cancer in vivo." (PMID 38110955, 2023). "ESRP1 has also been frequently reported to suppress tumor growth or metastasis in various cancers such as lung and pancreatic cancers." (PMID 38110955, 2023). "Other potential target proteins of ESRP1 in pancreatic cancer include IQ motif containing GTPase activating protein 1, heat shock protein 70, vimentin and perilipin 3, for which no splicing variants exist." (PMID 31963158, 2020). "Four, ESRP1 mRNA was significantly decreased in pancreatic cancer tissues and lymph node metastases and was inversely correlated with miR-23a expression." (PMID 29137308, 2017). "Taken together, our findings indicated that miR-23a functions as an oncogene by regulating ESRP1 in pancreatic cancer." (PMID 29137308, 2017). "ESRP1 can suppress cancer cell motility in head and neck carcinoma cell lines and ESRP1 protein expression is a favorable prognostic factor in pancreatic cancer." (PMID 28975893, 2017). "In pancreatic cancer, ESRP1 down-regulation promoted synthesis of the CD44s isoform, which further induces EMT." (PMID 29137308, 2017). "Further investigation showed that ESRP1 was a direct functional target of miR-23a in pancreatic cancer." (PMID 29137308, 2017). "Similar correlation between low ESRP1, low IIIb, and high IIIc variant expression for FGFR2 was demonstrated by IHC in pancreatic cancer." (PMID 27650542, 2016). "Similarly, circ-0092367 overexpression increased the protein levels of ESRP1 in pancreatic cancer cells by serving as a miR-1206 sponge." (PMID 38110955, 2023). "Similarly, the expression of ESRP1 enhanced the sensitivity of pancreatic cancer cells to gemcitabine." (PMID 38110955, 2023). "However, the evidence about the function of ESRP1 in pancreatic cancer still lacks and further studies are required." (PMID 31552163, 2019). "In breast and pancreatic cancer, ESRP1 down-regulation promoted synthesis of CD44s isoform." (PMID 29137308, 2017). "In this study, we determined the regulatory relationship between miR-23a and ESRP1, and proposed that miR-23a may promote pancreatic cancer EMT and metastasis via regulating CD44 splice isoform switching." (PMID 29137308, 2017). "Restoration of ESRP1 rescued the effect of miR-23a on pancreatic cancer cell progression." (PMID 29137308, 2017). "Furthermore, we examined the expression of ESRP1 mRNA in the three types of tissues and found that ESRP1 mRNA was significantly decreased in pancreatic cancer tissues and lymph node metastases and inversely correlated with miR-23a expression." (PMID 29137308, 2017). "Moreover, restoration of ESRP1 rescued the effect of miR-23a on CD44 splice isoform switching in pancreatic cancer cells." (PMID 29137308, 2017). "Thus, the inhibition of ESRP1 expression by miR-23a is essential for pancreatic cancer cell EMT and metastasis." (PMID 29137308, 2017). "Restoration of ESRP1 rescued the effect of miR-23a on pancreatic cancer cells." (PMID 29137308, 2017). "However, the potential regulatory network of splicing factors during the splicing process remains unclear and clarifying the function of ESRP1 is critical in the interpretation of the molecular mechanism of pancreatic cancer." (PMID 31552163, 2019).
pancreatic cancer (continued). "miR-23a increased alternative splicing of CD44v to CD44s and FGFR2 IIIb to IIIc via downregulation of ESRP1 expression by binding to its 3’ UTR, thereby promoting EMT and metastasis in pancreatic cancer." (PMID 38110955, 2023). "It has been established that in breast and pancreatic cancer ZEB1-driven EMT downregulates the expression of the RBP and splicing regulator ESRP1 as part of a self-enforcing feedback loop." (PMID 36346211, 2022). "An exception to this pattern has been observed in pancreatic cancer, where ESRP1 acts as a tumor suppressor while miR-23a, which directly targets the 3′UTR of ESRP1, promotes invasion and metastasis of cancer cells." (PMID 34769047, 2021). "Taken together, our results suggest that miR-23a partially promotes pancreatic cancer EMT and metastasis by targeting ESRP1 and regulating CD44 splicing as well as FGFR2 IIIb and FGFR2 IIIc mRNA levels." (PMID 29137308, 2017). "In agreement with the tumor suppressive role of ESRP1, several studies have shown that ESRP1 negatively regulates Epithelial-to-Mesenchymal Transition (EMT) in breast and pancreatic cancer, in oral squamous cell and non-small cell lung carcinomas." (PMID 28052020, 2017). "In summary, we identified a new mechanism by which miR-23a promotes pancreatic cancer cell EMT and metastasis by down-regulating ESRP1." (PMID 29137308, 2017). "Taken together, miR-23a may affect pancreatic cancer cell EMT and metastasis via regulating ESRP1 and its downstream factors." (PMID 29137308, 2017). "Interestingly, transient transfection of ESRP1 in PANC-1 cells led to an increase in expression of proteins including α-enolase, which is a prognostic marker in patients with pancreatic cancer, and filamin-α, which interacts with many proteins related to cancer metastasis." (PMID 31963158, 2020). "ZEB1correlates negatively with ESRP1 and positively with HAS2 in NCI-60 and CCLE cellline cohorts and in lung, breast, and pancreatic tumors, indicating that feedback loops operatingamong ZEB1, ESRP1, and HAS2 may modulate cancer cell plasticity across subtypes." (PMID 31069317, 2018).
lung carcinoma (19 papers, 2013 to 2025). "EMT is a key process by which lung cancer cells acquire migratory and invasive capabilities, and a high expression of ESRP1 is usually associated with the inhibition of EMT and the maintenance of cell epithelial properties." (PMID 40046628, 2025). "Alternative splicing of coactivator‐associated arginine methyltransferase 1 (CARM1) by epithelial splicing regulatory protein 1 (ESRP1) resulted in lung cancer cells sensitize to chemotherapy." (PMID 37168687, 2023). "ESRP1 expression is linked to poor survival and metastasis in lung cancer, and both ESRP1 and ESRP2 are upregulated in oral squamous cell carcinoma relative to normal epithelium." (PMID 31478829, 2019). "A deeper understanding of ESRP1’s specific mechanisms in lung cancer may pave the way for new diagnostic and therapeutic approaches." (PMID 40046628, 2025). "Furthermore, Pre‐NOL10 methylation and the splicing factor epithelial splicing regulatory protein 1 (ESRP1) worked together to downregulate circNOL10 expression in lung cancer, associated with significant inhibition of lung cancer development." (PMID 30693177, 2019). "Due to the correlation between ESRP1 expression in lung cancer and prognosis, it has potential as a therapeutic target." (PMID 40046628, 2025). "Previous studies have reported that circNOL10 is involved in cell proliferation and cell cycle progression of lung cancer through the methylation of splicing factor epithelial splicing regulatory protein 1 (ESRP1), but the role of NOL10 in HCC is implicit." (PMID 33102213, 2020). "From our previous identification of ZEB1-correlated genes in lung cancer using Affymetrix arrays, we had confirmed regulatory relationships for ST14, EpCAM, and ESRP1 upon ZEB1 gain- and loss-of-function." (PMID 24216980, 2013). "Targeting ESRP1 or its splicing events can affect the behavior of tumor cells and the tumor microenvironment, thereby affecting the occurrence, development, invasion, and metastasis of lung cancer." (PMID 40046628, 2025). "ESRP1 can affect the splicing patterns of multiple genes related to lung cancer." (PMID 40046628, 2025). "Therefore, the splicing factor ESRP1 can serve as a new marker molecule for drug resistance and a potential therapeutic target for patients with malignant lung tumors." (PMID 40046628, 2025). "Additionally, a recent study showed that circRNA epithelial splicing regulatory protein-1 (ESRP1) was significantly downregulated in chemoresistant lung cancer cells." (PMID 34295810, 2021). "Furthermore, ZEB1 expression in human bronchial epithelial cells directly repressed epithelial splicing regulatory protein 1 (ESRP1), leading to increased expression of a mesenchymal splice variant of CD44 and increment of EMT in lung cancer." (PMID 31126310, 2019). "Overall, these results suggested that the low circNOL10 expression levels relative to NOL10 mRNA in lung cancer cells may be a consequence of co‐regulation by ESRP1 and Pre‐NOL10 methylation." (PMID 30693177, 2019). "To investigate this hypothesis, we knocked down ESRP1 via two independent siRNAsin H1975—lung cancer cells that display a hybrid E/M phenotype stablyover multiple passages in vitro under normal culturingconditions." (PMID 31069317, 2018). "The expression and function of ESRP1 may vary in different types of lung cancer." (PMID 40046628, 2025). "Furthermore, alternative splicing of CD44 mRNA by ESRP1 enhances metastasis in lung cancer." (PMID 32467669, 2020). "Importantly, in both normal and lung cancer cells ESRP1/2 were regulated by ALK oncogenic activity." (PMID 27119231, 2016). "ESRP1 inhibits the EMT process by regulating the splicing of EMT-related genes, thereby reducing the migration and invasion of lung cancer cells." (PMID 40046628, 2025). "The RNA binding protein epithelial splicing regulatory protein 1 (ESRP1), for example, has been shown to regulate the splicing of CD44, and knockdown of ESRP1 was shown to suppress lung cancer metastasis." (PMID 38674106, 2024).
lung carcinoma (continued). "Epithelial splicing regulatory protein 1 (ESRP1) ISGylation attenuates its degradation, resulting in the suppression of EMT of lung cancer cells." (PMID 36319753, 2022). "More extensive lists of common ESRP1 AS events and target genes were obtained when the SW480 and HCT116 cell lines were individually compared with the lung cancer study." (PMID 36346211, 2022). "Relevant to the present study, ESRP1 was reported to regulate the EMT from CD44v (variable) to CD44s (standard) isoforms in breast and lung cancer progression." (PMID 36346211, 2022). "For example, in lung cancer cells, ZEB1 was shown to downregulate ESRP1 expression through direct binding to its promoter, contributing to a positive loop fostering EMT." (PMID 33158935, 2020). "circNOL10 downregulation in lung cancer cells was co‐regulated by Pre‐NOL10 methylation and the splicing factor ESRP1." (PMID 30693177, 2019). "According to their findings, circNOL10 could considerably hamper progress of lung cancer, while regulation of its expression was concurrent with methylation of its parental gene named Pre-NOL10 as well as intertwining factor of epithelial splicing regulatory protein 1 or ESRP1." (PMID 31481095, 2019).